MMP9 (matrix metallopeptidase 9)
Diseases named in the same sentence as MMP9 in open-access papers (continued):
Sharing a sentence is not in itself a finding about the gene and the disease.
Skin ulcer (3 papers, 2012 to 2022). A discontinuity of the skin exhibiting complete loss of the epidermis and often portions of the dermis and even subcutaneous fat. "Studies have shown that Nrf2-knockout skin ulcer wounds heal slowly, which is attributed to the high expression of MMP-9 in the cells." (PMID 36286472, 2022). "Besides, IGF-I treatment helped to restore the normal expression of both matrix metalloproteinase (MMP)-9 and tissue inhibitors of metalloproteinase (TIMP)-1 in diabetic rats with skin ulcers, indicating an important role of IGF-I in healing." (PMID 33860062, 2021).
sleeping sickness (3 papers, 2015 to 2021). "In some studies, the increasing levels of MMP-2 and MMP-9 correlated with the presence of parasites and leukocytes in the cerebrospinal fluid (CSF) of Trypanosoma brucei gambiense infected patients with the final stage of African sleeping sickness." (PMID 30572657, 2018). "In sleeping sickness, for instance, an increase in MMP-2 and MMP-9 favors leukocyte penetration into brain parenchyma, and parasite load and inflammation intensity in canine leishmaniosis." (PMID 33891967, 2021).
soft tissue sarcoma (3 papers, 2015 to 2021). A malignant neoplasm arising from muscle tissue, adipose tissue, blood vessels, fibrous tissue, or other supportive tissues excluding the bones. "Furthermore, increased secretion of MMP2 and MMP9 correlated with metastatic potential in bone and soft tissue sarcomas." (PMID 35145908, 2021).
Splenomegaly (3 papers, 2019 to 2025). Abnormal increased size of the spleen. "Additionally, mice receiving MMP9-in-1 displayed reduced splenomegaly and a significantly decreased spleen index compared to those of the CLP group." (PMID 41306770, 2025). "The increased fold induction of MMP-9 compared to VEGF at 6 w p.i. in serum was in line with the increased systemic disease at that endpoint in the 4T1- compared to the Py230-based TNBC model as also shown by the enhanced metastasis and splenomegaly data." (PMID 31921184, 2019).
staphylococcus aureus infection (3 papers, 2021 to 2023). An infectious process in which the bacteria Staphylococcus aureus is present. "In other models, such as in Staphylococcus aureus infection, Staphylococcal SuperantigenLike Protein 5, inhibits MMP-9 activity by binding to pro-MMP-9, in human neutrophils." (PMID 33891967, 2021). "Notably, 3 genes (NCF2, RAC2, and MMP9) were involved in Staphylococcus aureus infection, the most prevalent etiology of osteomyelitis in diabetic foot ulcer infections." (PMID 37904457, 2023).
testicular cancer (3 papers, 2019 to 2025). A primary or metastatic malignant neoplasm that affects the testis. "This scenario is supported by data from recent studies on testicular cancer cells, where PANX1 inhibition downregulates EMT genes, upregulates E-cadherin, downregulates MMP-9, and decreases cell invasion." (PMID 31817827, 2019). "In testicular cancer, inhibition Panx1 function hindered cell migration and invasion, and downregulated the expression of p-ERK1/2, vimentin and matrix metalloproteinase 9 (MMP9)." (PMID 40909173, 2025).
Thrombocytopenia (3 papers, 2009 to 2024). A reduction in the number of circulating thrombocytes. "Thrombocytopenia led to a significant reduction in intratumor PAI-1, MMP-3, MMP-9, and MPO, specifically in B16F1 tumors." (PMID 38493157, 2024).
tuberous sclerosis complex (3 papers, 2014 to 2023). "Bumetanide has also been tried as treatment for tuberous sclerosis which is a neurodevelopmental disorder associated with high MMP-9." (PMID 37430349, 2023). "MMP-9 protein levels were elevated in cortical lesions in patients with focal cortical dysplasia type IIb and tuberous sclerosis complex, which cause chronic epilepsy in children, suggesting a possible pathological role for MMP-9 in these intractable conditions." (PMID 26567100, 2014).
uremia (3 papers, 2017 to 2022). A clinical syndrome associated with the retention of renal waste products or uremic toxins in the blood. "The substantial neutrophil degranulation and intracellular reduction of key antibacterial proteins such as MPO, NE, and MMP-9 may result from persistent immune activation by uremia, the HD procedure, or the low-grade chronic inflammation seen in HD patients." (PMID 36284314, 2022). "PMet newborn presented increase in uremia and CRP and significant rise of active MMP-2 and MMP-9 forms." (PMID 28133545, 2017).
varicocele (3 papers, 2019 to 2023). A condition characterized by the dilated tortuous veins of the spermatic cord with a marked left-sided predominance. "In addition, the results of this study indicate that the inhibition of angiogenesis without downregulating VEGF and MMP-9 is one of the mechanisms of 100 mg/kg MOP inhibiting varicocele progression, but the underlying reason of this apparent controversy is still unclear." (PMID 31110554, 2019). "MMP-2 and MMP-9 have been found in the interstitium and seminiferous tubules, while the changes in MMPs in varicocele are controversial: decreased MMP-2 and MMP-9 levels have been reported in experimental varicocele, while a higher expression of MMP-9 has been reported in varicocele patients." (PMID 31110554, 2019).
venous ulcers (3 papers, 2021 to 2025). "Nanocrystalline silver dressings significantly reduce persistent venous ulcers and inflammatory markers MMP‐9 and MMP‐2 in a patient with chronic wounds, highlighting silver's anti‐inflammatory effects." (PMID 39707715, 2025). "In fact, studies show that MMP-2 and MMP-9 levels are particularly high in the tissues of subjects with venous ulcers in the active phase, and that levels are reduced significantly with the healing of the ulcer." (PMID 40362286, 2025). "Elevated MMP-2 and MMP-9 levels are commonly found in tissues affected by venous ulcers." (PMID 40362286, 2025).
ventilator-associated pneumonia (3 papers, 2015 to 2022). Serious INFLAMMATION of the LUNG in patients who required the use of PULMONARY VENTILATOR. "Although interpretation of the classification is sometimes difficult, it is possible that MMP-9 was chosen as a useful biomarker especially in patients with extensive infiltration because it was reported that plasma MMP-9 levels are associated with severity of ventilator-associated pneumonia." (PMID 31917802, 2020). "However, there are several reports of increased serum MMP-9 in patients with community-acquired or ventilator-associated pneumonia." (PMID 31917802, 2020). "Although increased levels of MMP8 and MMP9 of bronchoalveolar lavage fluid in earlier studies have been associated with severe infectious conditions such as ventilator associated pneumonias,the exact role of MMPs in inflammatory diseases of the lung is not yet understood." (PMID 26656474, 2015). "In patients with ventilator-associated pneumonia (VAP), circulating MMP-9 was significantly elevated in VAP patients and positively correlated with WBCs and neutrophils counts." (PMID 36482481, 2022).
Ventricular arrhythmia (3 papers, 2016 to 2024). "MMP-9-deficient mice were protected from ventricular arrhythmia." (PMID 27966586, 2016). "Here, we use translational approaches in animal models and human induced pluripotent stem cell-derived cardiomyocytes (hiPSC-CMs) to demonstrate the causal link between MMP-9 and ventricular arrhythmia, study the mechanisms underlying MMP-9 inhibition, and explore its translational potential." (PMID 27966586, 2016). "However, whether MMP-9 has a causal link to ventricular arrhythmia, as well as the underlying mechanism, remains unclear." (PMID 27966586, 2016). "In mice, myocardial MMP-9 inhibition modulates calcium homeostasis and reduces calcium leakage to prevent ventricular arrhythmia and its overexpression mediates gap junction (GJ) electrical uncoupling induced by Cx43 decreases in rat." (PMID 38533084, 2024). "Myocardial MMP-9 inhibition prevents ventricular arrhythmia through pleiotropic effects, including the modulation of calcium homeostasis and reduced calcium leakage." (PMID 27966586, 2016). "Feeding mice with doxycycline decreased MMP-9 activity and reduced ventricular arrhythmia after Ang II treatment." (PMID 27966586, 2016). "A dose-dependent reduction of ventricular arrhythmia was observed in comparisons of WT and MMP-9 heterozygous or homozygous knock-out mice." (PMID 27966586, 2016). "The pleiotropic effects employed by MMP-9 inhibition to prevent ventricular arrhythmia extend beyond ECM regulation and gap junction remodeling." (PMID 27966586, 2016). "The oral administration of doxycycline successfully prevented ventricular arrhythmia in the mouse model, thus demonstrating the potential translational significance of MMP-9 inhibition." (PMID 27966586, 2016). "Observational studies have established a strong association between matrix metalloproteinase-9 (MMP-9) and ventricular arrhythmia." (PMID 27966586, 2016). "Here, we investigated the mechanistic involvement of myocardial MMP-9 in the pathophysiology of ventricular arrhythmia." (PMID 27966586, 2016). "The present study extended our understanding of the role of MMP-9 in the pathogenesis of ventricular arrhythmia." (PMID 27966586, 2016). "MMP-9 deficiency consistently prevented PKA and pS2808 increases after Ang II treatment and reduced ventricular arrhythmia." (PMID 27966586, 2016). "MMP-9 activation in the ventricle increased the incidence of ventricular arrhythmia in our mouse model, whereas the down-regulation of MMP-9 by gene modification or pharmacological inhibition significantly reduced the incidence of ventricular arrhythmia." (PMID 27966586, 2016). "By downregulating MMP-9 and upregulating Cx43, NRG-1 reduces the dysfunctional electrical conductivity caused by acute MI, thereby improving cardiac electrophysiological parameters and reducing the susceptibility to ventricular arrhythmia." (PMID 36012430, 2022). "Ang II-induced ventricular arrhythmia vulnerability was completely prevented in the MMP-9−/− mice." (PMID 27966586, 2016). "MMP-9 inhibition might exert pleiotropic effects to prevent ventricular arrhythmia, including reduced cardiac fibrosis, gap junction remodeling and calcium homeostasis." (PMID 27966586, 2016). "The potential benefits of using MMP-9 inhibitors to treat ventricular arrhythmia are manifold." (PMID 27966586, 2016). "High MMP-9 levels were causally linked to ventricular arrhythmia in mouse models, and mice genetically deficient in MMP-9 presented a profoundly decreased vulnerability to ventricular arrhythmia." (PMID 27966586, 2016). "Doxycycline prevented ventricular arrhythmia, suggesting MMP-9 inhibition as a potential therapy." (PMID 27966586, 2016). "Further, elevated myocardial Matrix metalloproteinase-9 (MMP-9), a zinc-dependent endopeptidase that governs pathological cardiac remodeling processes like fibrosis and inflammation, is connected to ventricular arrhythmia." (PMID 38533084, 2024).
Ventricular arrhythmia (continued). "Rather, our results showed that MMP-9 and PKA inhibitors prevent calcium sparks and irregular calcium transients, which also prevented ventricular arrhythmia in mice and our modeled human hiPSC-CMs." (PMID 27966586, 2016). "Furthermore, a dose-dependent reduction in ventricular arrhythmia was observed between the WT, MMP-9+/− and MMP-9−/− mice." (PMID 27966586, 2016). "Furthermore, the mechanisms linking MMP-9 and ventricular arrhythmia have not been clearly described." (PMID 27966586, 2016).
ventricular dilatation (3 papers, 2012 to 2020). "Another experiment demonstrated that MMP-9-deficient mice exhibited attenuated ventricular dilatation and reduced collagen accumulation in response to left coronary occlusion." (PMID 29285294, 2017).
ventricular septal defect (3 papers, 2014 to 2025). The presence of a defect (opening) in the septum that separates the two ventricles of the heart. "For example, in humans, ALDOB (MIM: 612724) and MMP9 (MIM: 120361) have been found to be associated with ventricular septal defect." (PMID 38228144, 2024).
viral hepatitis (3 papers, 2014 to 2022). An acute or chronic inflammation of the liver parenchyma caused by viruses. "A recent study reports increased liver MMP-9 expression following I/R injury, and a correlation between serum MMP-9 and severity/progression of liver damage has been described in the setting of I/R injury, acute allograft rejection, and chronic viral hepatitis." (PMID 24592193, 2014).
viral myocarditis (3 papers, 2010 to 2020). Myocarditis that is caused by an infection with a viral agent. "Besides, suppression of uPA, MMP-2, and MMP-9 have been demonstrated to attenuate the remodeling and dysfunction of the left ventricle after acute pressure overload or viral myocarditis." (PMID 32354131, 2020). "In order to examine the effects of APN on cardiac MMP‐9 expression in inflammatory heart disease and to corroborate our in vitro results, WT and APN‐KO mice were subjected to CVB3 infection inducing viral myocarditis." (PMID 29263115, 2017).
Acanthamoebiasis (2 papers, 2018 to 2023). "Additionally, increased expression and activity of matrix metalloproteinases -2 and -9 (MMP-2 and MMP-9) were observed in the kidneys of hosts with systemic acanthamoebiasis." (PMID 38041167, 2023).
Acidosis (2 papers, 2013 to 2021). Abnormal acid accumulation or depletion of base. "Acidosis increased the expression of MMP3 and MMP9, enzymes which break down ECM components and accordingly, there were decreased levels of both collagen II and aggrecan recorded under acidic conditions." (PMID 33824228, 2021).
Acute encephalopathy (2 papers, 2014 to 2016). "The increase of the MMP-9 level and the MMP-9 to TIMP-1 ratio was observed in patients with acute encephalopathy after febrile seizures, what was associated with blood-brain barrier damage." (PMID 28104930, 2016). "Prolonged seizures were associated with high serum MMP-9 levels and increases in the ratio of MMP-9 to TIMP-1 in patients with acute encephalopathy with dysfunction of the blood-brain barrier following prolonged febrile seizures." (PMID 26567100, 2014).
Acute hepatitis (2 papers, 2012 to 2024). Acute hepatic injury resulting from inflammation typically accompanied by increased serum alanine transaminase activity. "This study also suggested that an inhibitory effect of hispolon on liver damage may have been due to the prevention of MMP-9 production in the development of acute hepatitis." (PMID 22013489, 2012).
acute monocytic leukemia (2 papers, 2021). Acute monoblastic leukemia (AML-M5), is one of the most common subtypes of acute myeloid leukemia (AML) that is either comprised of more than 80% of monoblasts (AML-M5a) or 30-80% monoblasts with (pro)monocytic differentiation (AML-M5b). "Additionally, the role of DENV in the regulation of MMP-9 was determined in human acute monocytic leukemia cell line (THP-1)." (PMID 34310658, 2021).
acute pericarditis (2 papers, 2011 to 2021). "To investigate whether IL-22 levels may be associated with mediators of lung pathology, we quantified MMP-9 levels in pericardial fluid and matching serum samples from 12 of the 22 TB pericarditis patients." (PMID 21767990, 2011). "Pericardial MMP-9 levels correlated positively with serum and pericardial levels of IL-22 from TB pericarditis patients." (PMID 21767990, 2011). "Additionally, we found that the accumulation of MMP9-positive neutrophils at early stages was required for mouse survival following angiogenesis and fibrosis, suggesting that MMP9-positive cells may play dual roles as tissue protectors against acute pericarditis as well as angiogenic inducers." (PMID 35187100, 2021).
adrenal tumors (2 papers, 2021 to 2022). "In this context, positive correlations between serum MMP-9 and baseline morning cortisol levels and between serum MMP-9 and cortisol concentrations after administration of dexamethasone were observed in patients with functioning adrenal tumors." (PMID 36213817, 2022). "In addition, the MMP-9 and MMP-8 serum levels were evaluated in patients with adrenal tumors prior and after surgery." (PMID 35201460, 2021). "The results suggested that MMP-9 may be useful in differentiating benign subclinical functioning adrenal tumors from benign nonfunctioning adrenal tumors." (PMID 35201460, 2021).
adrenocortical cancers (2 papers, 2021). "After surgery, MMP-8 and MMP-9 levels decreased significantly in patients with adrenocortical carcinoma, whereas the decrease in these MMPs in patients with benign tumors was not significant." (PMID 33578890, 2021). "High levels of MMP-8 and MMP-9 levels were found in patients with adrenocortical cancer, but were not indicative in differing malignancy." (PMID 33578890, 2021). "However, MMP-8 and MMP-9 levels were not increased in patients with inoperable adrenocortical cancers while MMP-1 level was not increased in patients with either benign or malignant adrenal tumors." (PMID 33578890, 2021).
Age-related cataract (2 papers, 2018 to 2020). A type of cataract (opacification of the lens) that forms during the course of aging. "Moreover, MMP-9 activity levels in LECs were measured in patients with diverse age-related cataracts, showing that the main MMP-9 activity was found in cortical cataracts." (PMID 33261005, 2020). "We found that the concentrations of IL-8, MMP-2, MMP-3, MMP-9, TGFβ-1, TGFβ-2, TGFβ-3, SAA, and TNF-α were significantly elevated in JIAU samples compared with the control group (senile cataract patients)." (PMID 29675026, 2018).
age-related hearing loss (2 papers, 2020 to 2021). "Consistent with the present result, the expression level of MMP9 in the primary auditory cortex was elevated in a model of age-related hearing loss." (PMID 32334536, 2020).
aging (2 papers, 2019 to 2020). A developmental process that is a deterioration and loss of function over time. "As MMPs are known to cause skin aging through the degradation of collagen, we also examined the activity of MMP-1 and the expression levels of MMP-1, MMP-2, and MMP-9." (PMID 30669248, 2019). "MMP-1 and MMP-9 are known to play a critical role in skin aging via collagen degradation." (PMID 32414118, 2020).
alcohol addiction (2 papers, 2018 to 2025). "When MMP-9 levels in plasma were measured in three distinct intoxicated states (light, moderate, and heavy) in cases of alcohol addiction, the results were all similar." (PMID 39997037, 2025).
anaplastic large cell lymphoma (2 papers, 2007 to 2013). Anaplastic large cell lymphoma (ALCL) is a rare and aggressive peripheral T-cell non-Hodgkin lymphoma, belonging to the group of CD30-positive lymphoproliferative disorders, which affects lymph nodes and extranodal sites. "Moreover, it has been reported that HSP90 and MMP-9 can constitute as a complex in anaplastic large cell lymphomas, and MMP-9 could be activated by HSP90 to promote cell invasion." (PMID 23638161, 2013).
anemia (2 papers, 2016 to 2024). A reduction in the number of red blood cells, the amount of hemoglobin, and/or the volume of packed red blood cells. "RPS14 deficiency leads to anemia, while overexpression rescued erythropoiesis, and this was linked to TGF-β-mediated MMP-9 expression." (PMID 38732249, 2024).
ankylosing spondylitis (2 papers, 2014 to 2023). An autoimmune chronic inflammatory disorder characterized by inflammation in the vertebral joints of the spine and sacroiliac joints. "Recently, the serum concentrations of both MMP-3 and MMP-9 have been found to be associated with disease activity in ankylosing spondylitis." (PMID 24490631, 2014).